RN7SL277P (RNA, 7SL, cytoplasmic 277, pseudogene)
Gene: Miscellaneous RNA gene on chromosome 1 (19,424,384 to 19,424,671, forward strand). Ensembl gene ENSG00000240490.
Homologues: Orthologues: chimpanzee Metazoa_SRP (97% identical), macaque Metazoa_SRP (35% identical). Paralogues in human: RN7SL1 (81% identical), RN7SL2 (81% identical), RN7SL3 (80% identical), RN7SL15P (79% identical), RN7SL408P (78% identical), RN7SL126P (77% identical), RN7SL480P (77% identical), RN7SL220P (76% identical), RN7SL296P (76% identical), RN7SL664P (76% identical), RN7SL797P (76% identical), RN7SL451P (76% identical), and 704 more.